BRD4 (bromodomain containing 4)
Diseases named in the same sentence as BRD4 in open-access papers (continued):
Sharing a sentence is not in itself a finding about the gene and the disease.
nut midline carcinoma (continued). "Bromodomain proteins have been implicated in a number of diseases; for example, NUT midline carcinoma (NMC) is caused by a mutation leading to a fusion between the BET bromodomain protein Brd4 and NUT, which produces the Brd4-NUT oncoprotein." (PMID 24704920, 2012). "NUT carcinoma is primarily considered an epigenetically driven cancer in which the BRD4–NUT–p300 axis promotes widespread chromatin hyperacetylation and activates the expression of SOX2, MYC, TP63, and likely other transcription factors to drive NC tumorigenesis and SCC phenotype." (PMID 41266112, 2026). "In addition, Western blotting analysis confirmed the correct size of the BRD4::NUTM1 fusion protein in mouse NUT carcinomas (mNCs)." (PMID 38724194, 2024). "Given that the BRD4-NUT fusion protein is the oncoprotein for NUT carcinoma, we constructed CMV-BRD4-NUT plasmid which can overexpress BRD4-NUT to simulate the pathogenic fusion gene of NUT carcinoma." (PMID 38130463, 2023). "However, the biologically-relevant molecules in Nut Carcinoma, the BRD4-NUT fusion protein and its interaction partner, full-length p300, collectively stimulate condensate formation and regulate transcription." (PMID 37488172, 2023). "Together, our data support a model in which the recruitment of active p300 into BRD4-NUT condensates rewires transcription to drive the gene expression program in Nut Carcinoma; however, the specific molecular features responsible for condensate formation and transcription are distinguishable." (PMID 37488172, 2023). "For example, BRD4-NUT is an oncogenic fusion protein that drives NUT carcinoma." (PMID 36358822, 2022). "However, recently, two primary lung BRD4::NUTM1 fusion carcinomas were reported that showed dual histology with areas typical of NUT carcinoma as well as foci of micropapillary carcinoma." (PMID 34997561, 2022). "Whereas TAD dysfunction due to boundary misregulation occurs in several cancers, including glioma and T-cell acute lymphoblastic leukemia, oncogenic hyperacetylated BRD4-NUT results in pathological long-range interactions within a novel nuclear sub-compartment in NUT carcinoma." (PMID 36358822, 2022). "Interestingly, the pathogenic fusion product of NUT (nuclear protein in testis) with BRD4 or BRD3 (BRD4-NUT or BRD3-NUT) causes NUT midline carcinoma (NMC), which is a rare but poorly differentiated and highly aggressive cancer of the squamous cell lineage that arises in midline structures." (PMID 33879235, 2021). "Our case is the first Brazilian case of NUT midline carcinoma with BRD4-NUT fusion." (PMID 31492174, 2019). "The BRD4-NUT fusion protein, which is produced by a gene reconstructed by a chromosomal translocation, activates multiplication related genes by hyperacetylating their chromatin with recruited p300, which causes NUT midline carcinoma (NMC)." (PMID 27827996, 2016). "WHSC1L1 was also reported to interact with BRD4 through the fusion product WHSC1L1-NUT (NSD3-NUT) observed in a rare squamous cell malignancy known as NUT midline carcinoma, while these cells underwent growth arrest and differentiation upon treatment with the bromodomain inhibitor JQ1." (PMID 27285764, 2016). "Its activity was first described in NUT midline carcinoma, a rare, aggressive epithelial cancer genetically defined by a chromosomal translocation of BRD4 with NUT, where JQ1 inhibition of BRD4 induced squamous cell differentiation and tumor regression in a tumor primagraft model." (PMID 25072021, 2014). "Notably, reprogramming of glycolytic metabolism and epigenetic histone modifications was observed in this unusual NUT carcinoma case, and this phenomenon was further confirmed by an in vitro cell culture model with bromodomain containing 4 (BRD4)-NUT overexpression." (PMID 38389647, 2024). "Brd4 is fused with NUclear protein in Testis (NUT) in most of the patients with NUT midline carcinoma (NMC)." (PMID 33802888, 2021).
nut midline carcinoma (continued). "Phase Ib trials included six solid tumors such as NUT midline carcinoma (NMC), which harbors an oncogenic form of BRD4, known as BRD4-NUT." (PMID 33322239, 2020). "We recently discovered that BRD4 is hyperphosphorylated in the highly lethal NUT midline carcinoma (NMC) to promote its target oncogene activation and tumor development." (PMID 32575711, 2020). "As an example, BRD4 promotes the expression of oncogenes, while the translocation of BRD3 or BRD4 to the NUT oncogene leads to its constitutive activity and is the cause of NUT midline carcinoma (NMC)." (PMID 31791394, 2019). "BRD4 has been shown to play a critical role in tumorigenesis in several cancers, and the BRD4-NUT fusion gene is a driver of NUT midline carcinoma (NMC), a rare but highly lethal cancer." (PMID 29540837, 2018). "The first clue linking Brd4 with cancer was the finding of Brd4-NUT fusion oncogene which was recognized as an important mechanism in NUT midline carcinoma (NMC), an aggressive form of squamous carcinoma." (PMID 24592384, 2014). "For example, chromosomal translocation leading to the expression of a fusion between BRD4 (or BRD3) and the nuclear protein in testis (NUT) is causative of a rare cancer form named NUT midline carcinoma (NMC)." (PMID 24497639, 2014). "NUT carcinoma (NC) is a rare exceptionally aggressive malignancy, defined by NUTM1 gene translocations, most commonly generating a BRD4::NUTM1 fusion that results in a poor prognosis and limited therapeutic options." (PMID 41754610, 2026). "Routine use of agnostic molecular investigations, including whole genome sequencing, identified a chromosome 15:19 translocation, with BRD4::NUTM1 gene fusion on RNA sequencing, confirming NUT carcinoma." (PMID 40277298, 2025). "We next investigated the functionality of Fi-dBET6 NPs in vitro using a patient-derived model of NUT midline carcinoma (NMC), a rare and aggressive squamous cell epithelial cancer driven by the BRD4-NUT fusion oncoprotein." (PMID 41348877, 2025). "In NUT midline carcinoma, the NSD3-NUT fusion interacts with BRD4 for BRD4-dependent transcription that is required for blockade of differentiation and sustaining cell proliferation." (PMID 41301842, 2025). "The less‐common fusion partner genes functionally interact with BRD4, highlighting the role of BET family protein‐mediated recruitment of NUT to chromatin in NUT carcinoma pathogenesis." (PMID 40336973, 2024). "BET inhibitor drugs are acetylated histone analogs that competitively inhibit the binding of fusion products such as BRD4-NUT, and clinical trials have demonstrated efficacy in the treatment of NUT carcinoma." (PMID 36936659, 2023). "The oncogenic fusion protein BRD4-NUT forms condensates and drives changes in gene expression in Nut Carcinoma." (PMID 37488172, 2023). "In our study, we introduced the BRD4-NUT oncogene into 3T3 cells to facilitate the formation of tumors both in vitro and in vivo, thereby simulating nut carcinoma and enabling further investigation." (PMID 38130463, 2023). "BRD4-NUT’s bipartite binding and activation of p300 in NUT carcinoma nucleates a feed-forward spread of histone hyperacetylation and chromatin condensation that sustains aberrant pro-proliferation gene transcription and perpetual tumor cell growth." (PMID 36690674, 2023). "NUT (Nuclear protein in Testis) is a testis-specific factor originally discovered as a chromosomal fusion partner of BRD4 and BRD3, both members of the BET double bromodomain-containing family of proteins, in an aggressive cancer known as NUT Carcinoma (NC)." (PMID 35565363, 2022). "Gene fusions of nuclear protein in testis (NUT) and BRD4, BRD3, or other genes are a characteristic of NUT carcinoma." (PMID 36077617, 2022). "The possibility of inhibiting BET proteins has been firstly explored, with good results, in NUT midline carcinoma (NMC), a rare subtype of squamous carcinoma characterized by the fusion oncoprotein BRD4‐NUT." (PMID 36051080, 2022).
nut midline carcinoma (continued). "Chromosomal translocation, involving the NUT gene fusing to the BET gene BRD4, creates an in-frame BRD4–NUT oncogene, resulting in NUT midline carcinoma." (PMID 32382065, 2020). "Silencing of the BRD4–NUT fusion gene with BETis prevents the differentiation and proliferation of NUT carcinoma cells." (PMID 32382065, 2020). "We further show that the BRD4-NUT/p300 chromatin condensation is important for transcriptional activation of pro-proliferation genes such as ALX1, a highly expressed oncogene in NUT carcinoma cells, and resulting ALX1/Snail signaling and epithelial-to-mesenchymal transition." (PMID 36690674, 2023). "BRD4-NUT, a driver fusion mutant in rare and highly aggressive NUT carcinoma, acts in aberrant transcription of anti-differentiation genes by recruiting histone acetyltransferase (HAT) p300 and promoting p300-driven histone hyperacetylation and nuclear condensation in chromatin." (PMID 36690674, 2023). "Non-NUT carcinoma cell lines transfected with BRD4-NUT alone did not undergo an oncogenic transformation, which indicates that other factors are required for oncogenic transformation." (PMID 34898574, 2021). "For example, translocation of bromodomain-containing protein 4 (BRD4) and formation of BRD4-NUTM1 fusion protein leads to a gain-of-function in the context of reading the histone acetylation in NUT midline carcinoma, and targeting BRD4 found effectively therapeutic in use." (PMID 34685645, 2021). "In NUT-midline carcinoma, a translocation that fuses the BRD3 or BRD4 protein to the NUT transcriptional regulator creates an oncoprotein that, through binding to acetylated histones, is thought to promote transcription of proliferation genes (e.g., MYC proto-oncogene)." (PMID 30634442, 2019). "NUT carcinomas lacking BRD4 fusion gene rearrangements are more differentiated and therefore possibly less aggressive." (PMID 28595655, 2017). "For example, BRD4 fusion with the nuclear protein in testis (NUT) gene expresses the BRD4-NUT oncoprotein, which plays an important role in the growth maintenance and differentiation block of the lethal malignancy NUT midline carcinoma (NMC)." (PMID 37142850, 2023). "NUT midline carcinoma (NMC) is a rare and aggressive squamous carcinoma subtype that is mainly driven by the BRD4-NUT fusion oncoprotein, and BET (bromodomain extra-terminal) inhibitors were found to have a high efficacy in treating NMC." (PMID 36361605, 2022). "It was reported that JQ1 competitively bound to the bromodomain of BRD4 and showed great antitumor efficacy in NUT midline carcinoma (NMC) with recurrent oncogenic translocation product, BRD4-NUT52." (PMID 34285329, 2021). "For example, translocation of BRD-containing BRD4 to NUTM1 in human cells generates an oncoprotein that drives a rare and aggressive form of squamous cell carcinoma, NUT midline carcinoma (NMC)." (PMID 32695779, 2020). "BET inhibitors are efficacious in models of NUT midline carcinoma (NMC), a rare epithelial tumor type driven by the fusions of NUT protein with either BRD3 or BRD4 genes." (PMID 24293458, 2013). "In addition, an in vivo study provided proof-of-concept for targeting BRD4 with a cell-permeable small molecule (JQ1) in NUT midline carcinoma (NMC), an aggressive squamous carcinoma that develops due to a fusion oncogene (e.g., NUT in frame with BRD4)." (PMID 37198402, 2023). "This property grants the drug with the capacity to abrogate cell proliferation in vitro and to inhibit tumor growth in mice xenografted with a panel of cell lines bearing different BRD4–NUT translocations, thus suggesting a therapeutic potential for the treatment of NUT midline carcinoma (NMC)." (PMID 31581671, 2019). "However, the BRD4-NUT fusion and the lack of SCC molecular signature in NUT carcinoma makes this relationship somewhat controversial." (PMID 33351171, 2021).
nut midline carcinoma (continued). "One study that included 124 patients of NUT carcinoma found that the mOS of nonthoracic primary NUT carcinoma was significantly better than that of thoracic primary NUT carcinomas, and patients with BRD4-NUT fusion had worse mOS than those with BRD3-NUT or NSD3-NUT fusion." (PMID 34660264, 2021).
ovarian carcinoma (67 papers, 2015 to 2026). A malignant neoplasm originating from the surface ovarian epithelium. "Next, we mimic BRD4 focal deletions using CRISPR-Cas9 technology and show that these focal deletions rescue ovarian cancer cells from toxicity associated with BRD4 overexpression, suggesting that BRD4 levels must be fine-tuned for cancer cell proliferation." (PMID 40112818, 2025). "We further selected OVSAHO ovarian carcinoma cells as a model to validate the toxic effects associated with BRD4 overexpression from the ORF screen data." (PMID 40112818, 2025). "Another research in ovarian cancer found that PRMT1-mediated BRD4-ADMA modification is associated with TGF-β signaling and promotes metastasis and invasion." (PMID 40612681, 2025). "Amplification of BRD4 is frequently associated with chemoresistant ovarian carcinoma, but little is known about the biological effects of the overexpression of BRD4 isoforms in this malignancy." (PMID 37705995, 2023). "Taken together, our in vivo findings indicate that the overexpression of BRD4, particularly BRD4-L isoform is associated with chemotherapy resistance in ovarian cancer." (PMID 37705995, 2023). "Given that BRD4-R179/181/183 methylation is critical for BRD4-ADMA formation, we next construct BRD4-WT and the methylation-deficient mutant of BRD4-R3K in ovarian cancer cells." (PMID 37737256, 2023). "In ovarian cancer cells, miR-765 mainly located at the cytosol fraction where it directly associated with BRD4 mRNA." (PMID 33686960, 2021). "BRD4 binds to the promoter regions of NOTCH3 in ovarian carcinoma, and inhibition of BRD4 activity is associated with lower expression of NOTCH3 mRNA and protein, as well as the expression NOTCH3 target genes." (PMID 34758842, 2021). "In ovarian cancer patients, the increased activity of BRD4 is associated with the higher expression of a variety of oncogenes, many of which are positively regulated by BRD4 on transcriptional level." (PMID 34758842, 2021). "BRD4 gene and protein expression will be subsequently associated with prognosis in ovarian cancer." (PMID 38893083, 2024). "It is now clear that BRD4 could serve as a novel target in ovarian cancer like BRCA1/2 mutations and HR deficiency." (PMID 38893083, 2024). "Moreover, we demonstrated that an overexpression of BRD4 isoforms is associated with chemoresistance in ovarian cancer." (PMID 37705995, 2023). "Next, we investigated if the ovarian cancer phenotype associated with the overexpression of individual BRD4 isoforms, such as increased cell proliferation or chemoresistance could be recapitulated in vivo." (PMID 37705995, 2023). "Nevertheless, the study of BRD4-associated super-enhancers in ovarian cancer may lead to the identification of biomarkers, downstream druggable targets, and a better understanding of the regulatory processes that drive this disease." (PMID 35869079, 2022). "Studies show that in addition to BRD4 gene amplification resulting in increased expression of BRD4 isoforms in ovarian cancer, the increased BRD4 protein abundance could be associated with decreased ubiquitination, or increased de-ubiquitination as observed in other types of tumors." (PMID 37705995, 2023). "Moreover, we disclose that asymmetric methylation by PRMT1 was required for BRD4 phosphorylation and BRD4-induced ovarian cancer cell migration and invasion, which may be associated with transforming growth factor-β (TGF-β) signaling." (PMID 37737256, 2023). "Clinically, BRD4 is highly expressed in ovarian cancer and independently predicts poor survival, outperforming FOXM1 and MYC." (PMID 41820523, 2026). "In this study, we have highlighted the biological relevance of fine-tuning BRD4 expression in ovarian cancer cells, as too-high or too-little levels of gene expression become detrimental to cancer cell growth." (PMID 40112818, 2025).